INS (insulin)
Diseases named in the same sentence as INS in open-access papers (continued):
Sharing a sentence is not in itself a finding about the gene and the disease.
Insulin resistance (continued). "While some studies reported a strong relationship between high salt intake and insulin resistance in human and animal models, others showed a hyperinsulinemic response to an oral glucose overload and an accentuated impairment in whole-body insulin sensitivity related to salt restriction." (PMID 29509671, 2018). "Serine phosphorylation of IRS-1 suppresses insulin signal transduction in a variety of cell backgrounds, which might contribute to peripheral insulin resistance." (PMID 30225267, 2018). "Insulin resistance may be defined as a condition where a normal or elevated insulin concentration produces a failed metabolic response." (PMID 29772703, 2018). "Overweight and obese individuals frequently acquire metabolic complications where gradually increasing defects in insulin signaling result in chronic hyperinsulinemia (pre-type 2 diabetes; pre-T2D), insulin resistance (overt-T2D), and impaired insulin secretion (late-T2D)." (PMID 30524378, 2018). "Although insulin secretion maintains blood glucose levels within the normal range, most individuals with insulin resistance, such as the overweight and obese subjects in our study, may have impaired insulin secretion and defective insulin action." (PMID 30558330, 2018). "In recent years, type 2 diabetes and its prodromal state, insulin resistance (a pathological condition in which cells fail to respond normally to the hormone insulin), have been identified as risk factors for developing sporadic AD." (PMID 29743868, 2018). "In addition, it aimed to determine the relationships between HMW adiponectin and insulin, insulin resistance, NEFA, 8-isoprostane, oxidized LDL-C, high sensitivity C-reactive protein (hsCRP) in women with SHS exposure." (PMID 30356972, 2018). "However, VLC rats had higher than feed-deprived insulin levels at 3 h after the oral load (p < 0.05); such persistent elevation in insulin levels is consistent with insulin resistance in VLC rats." (PMID 31061673, 2018). "Recent data from our laboratory showed that the levels of intracellular HSP72 (iHSP72) is positively correlated with insulin signaling (sensitivity), while the eHSP72 may induce inflammation and insulin resistance." (PMID 29983896, 2018). "Besides improvements in plasma insulin levels, insulin resistance index, and plasma adiponectin levels, changes in caecal SCFA content and IM composition were measured by gas chromatography and real-time PCR." (PMID 29086061, 2018). "In genome-wide association studies (GWAS), it was also found that the LRP1 single nucleotide polymorphism (SNP), rs4759277, is strongly linked to phenotypic alterations of the carbohydrate metabolism, such as fasting insulin, C-peptide and homeostasis assessment of insulin resistance." (PMID 29914093, 2018). "Similarly, siRNA knock down of the key regulatory proteins in CoQ biosynthesis that were down-regulated in insulin-resistant mouse and human adipose tissue (Coq7 or Coq9) lowered mitochondrial CoQ9 and triggered insulin resistance." (PMID 29402381, 2018). "The autoimmune beta cell destruction in the pancreas is the cause of insulin-dependent type 1 diabetes (T1D), whereas insulin resistance (IR) or inadequate insulin release is the cause of non-insulin-dependent diabetes (T2D)." (PMID 29808089, 2018). "Moreover, in vitro models should also elicit metabolic responses, for example retain their insulin sensitivity but also show signs of insulin resistance in pathophysiological conditions." (PMID 30250238, 2018). "They found that treatment of lean recipient mice with macrophages exosomes derived from adipose tissue collected from obese mice led to transfer of miRNAs to insulin sensitive tissues (muscle, liver, and adipose tissue) leading to impairment of glucose tolerance and enhancing insulin resistance." (PMID 30469501, 2018).
Insulin resistance (continued). "Insulin resistance triggered by pharmacological or genetic inhibition of CoQ biosynthesis occurred independently of consistent defects in insulin signalling to the key regulators of glucose transport (Akt or the Akt substrate TBC1D4), or changes in GLUT4 expression." (PMID 29402381, 2018). "Indeed, there is a decrease in insulin secretion and increased insulin resistance in elderly patients." (PMID 30186783, 2018). "The result suggested that high-dose GD improved insulin sensitivity and insulin resistance." (PMID 30337946, 2018). "Moreover, GBE enhanced insulin sensitivity and prevented insulin resistance by increasing insulin-induced Akt phosphorylation and insulin receptor substrate 1 expression." (PMID 29682154, 2018). "Furthermore, fasting insulin concentration and insulin resistance decreased only in the real rTMS group." (PMID 30555295, 2018). "However, we believe the study still allows meaningful observations to be made concerning insulin signaling and insulin resistance in premature baboons." (PMID 30540820, 2018). "The heart is an insulin-responsive organ, and the presence of insulin resistance and obesity (as previously demonstrated in post-term children) could underpin the altered cardiac function." (PMID 30154437, 2018). "However, an inverse association was seen between the serum HWM adiponectin and the insulin levels and insulin resistance among the women with SHS exposure." (PMID 30356972, 2018). "In another study, chromium, biotin, or their combination significantly upregulated PPAR-γ expression in adipose tissue, which might have an effective insulin-sensitizing impact and reduce insulin resistance in a diabetic rat model." (PMID 30546347, 2018). "Our findings fit with the accelerator hypothesis, which proposes that insulin resistance plays a role in promoting autoimmune diabetes by increasing the insulin demand—this may accelerate disease onset in individuals with an ongoing autoimmune process." (PMID 29589073, 2018). "HC use has been associated with insulin resistance, manifested by reduced peripheral tissue insulin sensitivity, however this association has not been shown to be related to 9p21 genotype elsewhere." (PMID 30138332, 2018). "It was recognised early on that discovery of loci associated with insulin resistance was facilitated by accounting for differences in obesity levels; GWAS of insulin resistance have since been conducted based on fasting insulin levels adjusted for BMI [35••, 37–39]." (PMID 29779155, 2018). "Insulin resistance (IR) refers to the reduced biological efficacy of insulin on effector organs." (PMID 30347867, 2018). "For instance, cinnamon, a spice that is high in polyphenols, improves insulin sensitivity, alleviates peripheral insulin resistance, limits the stress-induced oxidation, especially in diabetic rats, and is neuroprotective of the cerebral tissue of rats exposed to high fat diet." (PMID 29813096, 2018). "The results indicate that insulin resistance, accompanied by changes in insulin-sensitive brain regions, might accelerate cognitive decline." (PMID 30400348, 2018). "Increased insulin resistance may attenuate increased lipolysis inhibition in people with higher fasting insulin levels." (PMID 30541568, 2018). "Notably, circulating adiponectin is inversely correlated with obesity and insulin resistance, and has insulin sensitizing effects on skeletal muscle and liver." (PMID 29570618, 2018). "Undercarboxylated osteocalcin (ucOC) increases insulin release and insulin resistance in mice." (PMID 30693288, 2018). "Participants with a higher value of dietary TAC had significantly lower insulin concentration and homeostatic model assessment of insulin resistance (HOMA-IR) as well as less hepatic fat accumulation (p < 0.05 for all comparisons) than those with lower values of dietary TAC." (PMID 30463312, 2018).
Insulin resistance (continued). "Although various signaling pathways are related to hepatic insulin sensitivity, it has been reported that ER stress-induced inflammasome activation contributes to hepatic inflammation and steatosis, which are major contributors to hepatic insulin resistance." (PMID 30134566, 2018). "At a cellular level, hyperinsulinaemia may exacerbate insulin resistance, disrupting insulin action at several points within the signalling cascade, in a cell-specific manner." (PMID 28852804, 2017). "We have previously demonstrated that the diet induced insulin resistance associated with a significant rise in serum insulin but not glucose levels." (PMID 28302152, 2017). "While both ob/ob; ARC +/+ and ob/ob; ARC −/− mice exhibited severe insulin resistance as demonstrated by the need to employ a high dose of insulin (5 U/kg) to decrease blood glucose concentrations, deletion of ARC exacerbated this abnormality to only a minor degree." (PMID 28765602, 2017). "However, there is a clear effect of Lepr genotype on insulin resistance in females, with fatty animals being insulin resistant." (PMID 29211750, 2017). "SFC also greatly increased plasma insulin level with slight improvement of insulin resistance." (PMID 29018279, 2017). "Insulin resistance or hyperinsulinemia may be related to bone mass because insulin plays an important role in the anabolic effects on bone mass." (PMID 28704413, 2017). "Moreover, biochemical markers reflecting insulin resistance such as HbA1c, insulin, C-peptide, and HOMA-IR showed more durable improvement in RY compared to BI." (PMID 29216250, 2017). "The effect of Heqi San on insulin resistance may also be due to an improvement in beta cell function, which is directly responsible for insulin secretion." (PMID 29020999, 2017). "Insulin resistance (IR) is characterized by the failure of target cells, including adipose, pancreas, skeletal muscle and liver tissues, to respond to normal levels of circulating insulin." (PMID 28492722, 2017). "Our data appear to indicate that insulin (FI and PI) and insulin resistance (HOMA-IR) may have a significant mediating effect on the association between BMI or WC and BP, which accounted for about 25~40% of the total effect of this association." (PMID 28710353, 2017). "Moreover, success of the insulin resistance model was further confirmed by an obvious reduction in insulin-stimulated glucose uptake shown in the PA–LPS group." (PMID 29096724, 2017). "In addition, the pigs also displayed intense insulin secretion, glucose intolerance and skeletal muscle insulin resistance." (PMID 29046729, 2017). "Thus, our patients showed insulin resistance of glucose metabolism and lipolysis, hyperinsulinemia and insulin hypersecretion, dyslipidemia, reduced levels of adiponectin, and raised circulating levels of markers of inflammation." (PMID 28827671, 2017). "Indeed, PPAR-γ activation, by TZD or other agonists, improves insulin resistance and reduces circulating levels of insulin and free IGF-I." (PMID 28275367, 2017). "In conclusion, our study suggests indicates that FABP4 may not only be an effective marker of insulin resistance in skeletal muscle, but also enhances insulin secretion." (PMID 28654680, 2017). "DAG/PKCθ activation is shown to induce insulin resistance by impairing insulin signaling in muscle." (PMID 28261091, 2017). "In addition, high-fat diet diminished CEACAM1 expression and induced impaired insulin clearance, hyperinsulinemia and insulin resistance in C57/BL6J mice, and these effects were counteracted by liver-specific inducible CEACAM1 expression." (PMID 28469173, 2017). "However, we observed an increase in both total and HMW-adiponectin in both STD-GSPE and CAF-GSPE animals, which was accompanied by hyperinsulinemia and increased insulin resistance and decreased insulin sensitivity." (PMID 28974704, 2017).
Insulin resistance (continued). "hs-CRP has also been related to adiposity and insulin resistance, which might explain the association of IL-1RA and hs-CRP with adverse changes in adiposity and insulin sensitivity in our prospective study." (PMID 28911155, 2017). "Using a stepwise bidirectional regression model adjusted for the effects of age, sex and body mass index (BMI), the contribution of FFAR4 SNPs to the variance of baseline index values of homeostatic model assessment of insulin resistance (HOMA-IR) or insulin levels was estimated." (PMID 29113108, 2017). "The aim of this study was to evaluate the association between insulin resistance and thyroid pathology in obese patients, and compare the results between insulin-resistant and noninsulin-resistant patients." (PMID 29412382, 2017). "Thus high-fat-fed Px rats exhibit the characteristics of type 2 diabetes, with both insulin resistance and impaired insulin secretion (random glucose levels > 180 mg/dL)." (PMID 29104217, 2017). "These insulin signaling pathways could be targeted with new or existing medicines to potentially help brain insulin resistance and possibly reduce or even improve cognitive decline." (PMID 28070499, 2017). "We studied three pancreatic hormones (insulin, glucagon, C-peptide) related to insulin resistance." (PMID 27465935, 2017). "Indeed, SGLT2 inhibitors (SGLT2i) reduce plasma glucose levels by inhibiting glucose reabsorption, without targeting the major pathophysiological defects in T2D (insulin resistance and impaired insulin secretion)." (PMID 28128227, 2017). "In obesity, insulin resistance develops as a consequence of metaflammation in which elevated circulating levels of pro-inflammatory cytokines such as TNFα and IL-6 negatively affect the insulin signaling cascade." (PMID 28233125, 2017). "Glucose/insulin levels during OGTT were used to calculate insulin resistance/sensitivity indexes." (PMID 29113405, 2017). "Moreover, plasma insulin was significantly elevated to 0.51 ± 0.155 ng/ml, clearly indicating pre-diabetic insulin resistance as reported by other studies using similar diets." (PMID 29249964, 2017). "Thus, the link between inflammatory and insulin pathways has been established and suggested a role of inflammation in the development of insulin resistance in adipocytes." (PMID 28912810, 2017). "Insulin resistance might be considered to be responsible for the increase in the secreting load of islet β-cells and insulin secretion during the compensatory period." (PMID 28372564, 2017). "Insulin response to elevated glucose levels indicated neither absolute insulinopenia nor insulin resistance, however suggested a relative insulin deficiency." (PMID 28588004, 2017). "Leptin may contribute to insulin resistance and its metabolic correlates and appears to have a direct pro-thrombotic effect, in addition to acting synergistically with insulin and free fatty acids to stimulate sympathetic activity and vasoconstriction." (PMID 27598976, 2017). "Furthermore, a significant relationship was found between the rs7566605 and insulin, homeostasis model of assessment-insulin resistance, the percentage of body fat, fat mass, leptin, and adiponectin." (PMID 28160769, 2017). "This inflammatory response affects insulin signalling in the cells, promoting insulin resistance, as well as glucose metabolism, and together may indirectly promote an increase in insulin production by pancreatic beta cells." (PMID 28651594, 2017). "We intend to demonstrate that GLP-1 analogues could be used as new tools for the treatment of these metabolic and adipose tissue disorders, reducing fat mass and insulin resistance, decreasing insulin requirements, and improving A1c." (PMID 28086952, 2017). "Taken together, our data support the concept of spaceflight-induced alterations in the response to insulin that may correlate with insulin resistance." (PMID 28542224, 2017).
Insulin resistance (continued). "In addition, fish proteins have been observed to have beneficial effects on both insulin sensitivity and insulin resistance in rats." (PMID 28282859, 2017). "In T1DM, insulin resistance is thought to be due to hyperglycemia producing down-regulation of glucose transporters and the disruption of fatty acid regulation producing post-transport regulation of insulin activity." (PMID 29207492, 2017). "In addition, moderate alcohol consumption can lead to reductions in insulin secretion and improvements in insulin resistance (Lazarus, Sparrow, & Weiss, 1997)." (PMID 28638713, 2017). "Obesity is characterized by increased fat mass, insulin resistance, hyperinsulinemia, and an increased risk not only for type 2 diabetes but also for cancer; acromegaly is also characterized by insulin resistance but with decreased fat mass, and an excess of GH, insulin, and IGF1." (PMID 28316059, 2017). "Leptin enhances peripheral insulin sensitivity and improves pancreatic β-cell function.These normal functions of leptin are disrupted in leptin resistance state of pregnancy inducing insulin resistance and impaired glucose tolerance in pregnancy." (PMID 28732072, 2017). "To determine whether the PGC-1α overexpression observed in patients infected with HCV was correlated with systemic insulin resistance, we measured fasting glucose and insulin levels on the day of the liver biopsy." (PMID 28733598, 2017). "Thus, we suggest that CML has a greater effect on insulin secretion ability than on insulin resistance." (PMID 28695132, 2017). "Insulin resistance, a status of impaired insulin function, leads to decreased ammoniagenesis in the renal tubule, resulting in acidic urine which may promote uric acid stones." (PMID 29073130, 2017). "Of note is that pigs rarely develop insulin resistance, which may be the result of artificial selection for high meat production and, thereby, high pancreatic insulin secretion and tissue insulin sensitivity for energy storage, especially in adipose tissues." (PMID 28253305, 2017). "Naringin treatment ameliorates these metabolic complications by reducing glucose intolerance, insulin resistance and increased insulin sensitivity hence could possess metformin-like effects." (PMID 29121676, 2017). "However, no large population-based prospective studies have evaluated GlycA as a predictor of changes in insulin secretion, insulin sensitivity, or insulin resistance-related traits." (PMID 28911155, 2017). "Moreover, circulating SFRP4 levels are positively correlated with glucose, insulin, glycated hemoglobin and the homeostasis model assessment of insulin resistance (HOMA-IR) values." (PMID 29037197, 2017). "Unlike type 2 DM, associated with insulin resistance and affecting metabolism in virtually all tissues, type 1 DM in non-obese adults, if adequately substituted with insulin, provides the purest available form of DN." (PMID 28359252, 2017). "Indeed, in T1D patients, the mean insulin dose is generally increased in overweight subjects due to insulin resistance." (PMID 29112131, 2017). "The authors suggest that this increased insulin secretion might be a compensatory mechanism to overcome initial insulin resistance." (PMID 28632742, 2017). "Therefore, the use of insulin sensitizers has been proposed to reduce insulin resistance and its complications." (PMID 29184536, 2017). "Interestingly, we observed strong correlations between TCA and TCDCA concentrations and plasma insulin levels, the index of insulin resistance, and ATM markers (q values below 0.0005 for insulin and index of insulin resistance)." (PMID 28166818, 2017). "Prevent body weight gain and reduce serum insulin levels and insulin resistance." (PMID 29167659, 2017). "Consequently, the insulin resistance can reduce the responses of adipose tissues to inhibitory effects of insulin." (PMID 28107442, 2017).